CLDN18 (claudin 18)
Diseases named in the same sentence as CLDN18 in open-access papers (continued):
Sharing a sentence is not in itself a finding about the gene and the disease.
gastric cancer (continued). "In 2014, the fusion of ARHGAP26 and CLDN18 (CLDN18-ARHGAP26 fusion) was first reported in gastric cancer patients." (PMID 34716859, 2022). "GC cells knocked down by CLDN18 promoted gastric cancer cell proliferation and infiltration compared to the controls." (PMID 35053454, 2022). "On the one hand, CLDN18.2 positivity is more common in advanced gastric cancer than in early (stage I and II) gastric cancer." (PMID 35811317, 2022). "The underlying mechanism of the effects of CLDN18-ARHGAP26 fusion protein on the downstream molecules to cause tumorigenesis and progression of gastric cancer also needs to be further studied." (PMID 34716859, 2022). "The FAST study identified claudin-18 (CLDN18.2) as a promising novel therapeutic target for gastric cancer (GC)." (PMID 35811317, 2022). "We aimed to assess putative correlations between claudin 18.2 expression and pathological or prognosis features in patients with gastric cancer." (PMID 33747967, 2021). "In general, the CLDN18.2 expression level in the metastatic lesions was relatively consistent with that in the corresponding primary gastric cancer tissues." (PMID 31182754, 2019). "Recent studies have identified CLDN18-ARHGAP26/6 fusions in gastric cancers, with predominance in diffuse-type gastric cancers (DGCs)." (PMID 31182754, 2019). "Use of monoclonal antibodies for claudin targeting led to very promising in vivo results; in particular with anti-Cldn18 or -Cldn1 antibodies for treatment of gastric cancer or HCV infections, respectively." (PMID 31561440, 2019). "Claudin-7 expression correlated with shorter overall survival in gastric cancer patients, while the overall survival was increased in patients with claudin-18 expression." (PMID 31861759, 2019). "Recently, claudiximab was reported to be a first-in-class chimeric monoclonal antibody for the treatment of gastric cancer targeting claudin-18, which is an important factor in gastric cancer metastasis." (PMID 31861759, 2019). "In fact, an anti-CLDN18 monoclonal antibody, claudiximab, has been developed for gastric cancers and is currently being evaluated in clinical trials." (PMID 30034621, 2018). "To validate this finding, we evaluated the effect of CLDN18-ARHGAP26 overexpression on the migration ability of human gastric cancer cells." (PMID 30361512, 2018). "In the FISH analysis, split signals of the CLDN18 gene were identified in all RT-PCR positive gastric cancers." (PMID 30034621, 2018). "Ectopic expression of CLDN18-ARHGAP26 also enhanced the invasion capacity of these human gastric cancer cells (P < 0.001, Wilcoxon signed rank test)." (PMID 30361512, 2018). "These functional data suggest that CLDN18-ARHGAP26 confers the metastatic phenotype on gastric cancer by enhancing migration and invasion capacities." (PMID 30361512, 2018). "Considering these observations, it has been postulated that CLDN18-ARHGAP26/6 fusions significantly impact the clinical behavior of gastric cancers." (PMID 30034621, 2018). "Most (4 out of 6) of the gastric cancers with distant organ metastases were CLDN18-ARHGAP26/6 fusion-positive." (PMID 30034621, 2018). "Given that cell migration/invasion activities are regulated by complex crosstalk between RHO GTPases38–40, further biochemical studies are warranted to explore how CLDN18-ARHGAP26 affect the migration/invasion activities of gastric cancer cells." (PMID 30361512, 2018). "CLDN18-ARHGAP26/6 fusions have been identified in gastric cancers, with a predominance in diffuse-type gastric cancers (DGCs)." (PMID 30034621, 2018). "To figure out the role of CLDN18-ARHGAP26 fusion in gastric cells, we stably expressed CLDN18-ARHGAP26 in a gastric cancer cell line (i.e., BGC-823)." (PMID 29961079, 2018). "In summary, we investigated the clinicopathological characteristics of CLDN18-ARHGAP26/6 fusion-positive gastric cancers and found that fusion-positive DGCs have strong metastatic ability, a phenotype that is more obvious in younger patients." (PMID 30034621, 2018).
gastric cancer (continued). "Of the three claudins we identified to interact with an HIF-1 network, CLDN1 and CLDN4 were previously reported as upregulated in gastric cancer progression, while CLDN18 was downregulated." (PMID 29050243, 2017). "Downregulation of claudin-18 has been shown to be related to proliferation and migration of gastric cancer cells." (PMID 28350854, 2017). "The most innovative point of this study is that the combination of CDH17 and CLDN18 demonstrated homogeneous and robust expression in more than 90% cases of gastric cancer, even in diffuse-type cases." (PMID 27580354, 2016). "Secondly, just two markers, CDH17 and CLDN18, was sufficient to account for more than 90% of gastric cancer cases." (PMID 27580354, 2016). "Down-regulation of miR-1303 prevents proliferation, migration, and invasion of gastric cancer cells mediated by up-regulation of claudin-18." (PMID 26061016, 2015). "The expression level of stomach Cldn‐18 is significantly downregulated in atrophic gastritis and gastric cancer in humans." (PMID 24744879, 2014). "Transfection of claudin-18 small interfering RNA (siRNA) was accomplished in MKN74, a claudin-18-positive gastric cancer cell line, to investigate the effect of claudin-18 on proliferation and invasion of cancer cells." (PMID 24073219, 2013). "Claudin-18 was significantly down-regulated in gastric cancer compared to surrounding gastric normal mucosa or intestinal metaplasia." (PMID 24073219, 2013). "It has been reported that claudin-18 expression has been shown to have prognostic value in gastric cancer and claudin-3,-4 and-7 expression are similarly elevated in gastric cancer." (PMID 23919729, 2013). "The seven RNAs upregulated in gastric cancer were CLDN18, EPCAM, REG4, BBC3, OLFM4, PPARG, and CDH17, while the two downregulated genes were IFITM1 and HIF1A." (PMID 22929309, 2012). "For example, claudin-1 expression has been shown to have prognostic value in colon cancer, claudin-18 in gastric cancer, and claudin-10 in hepatocellular carcinoma." (PMID 16836752, 2006). "CLDN18-ARHGAP fusion gene is enriched in younger-onset gastric cancer." (PMID 40687428, 2025). "Future research should prioritize the optimization of predictive biomarkers through the development of circulating tumor DNA (ctDNA)-based strategies for monitoring molecular response, as well as the relative abundance and activity of tumor cells in CLDN18.2-positive gastric cancer." (PMID 40900784, 2025). "This may prove to be an effective BsAb in the treatment of HER2-positive and/or CLDN18.2-positive gastric cancer, potentially overcoming resistance to, e.g., Trastuzumab." (PMID 40862764, 2025). "Of the 17 CLDN18.2-positive patients, 12 had gastric cancer (GC)." (PMID 40862764, 2025). "Research on CLDN18 has made significant advancements, particularly in relation to gastric cancer." (PMID 40936686, 2025). "Cldn18 is a tight junction protein specifically expressed in gastric epithelial cells and is frequently downregulated in human gastric cancer, while also serving as a target for novel therapeutic approaches including CAR-T cell therapy and antibody-drug conjugates." (PMID 40673273, 2025). "Meanwhile, we observed that intravenously injecting mice with the same number of CLDN18.2-GFP gastric cancer cells in combination with CAFs significantly increased the incidence of pulmonary embolism and led to a higher mortality rate compared to the control group." (PMID 38200591, 2024). "Importantly, we reported for the first time that CLDN18.2-directed ADCs induced cytoprotective autophagy in gastric cancer treatment, with involvement of the Akt/mTOR signaling pathway." (PMID 39227365, 2024). "Patient 9, a woman with advanced gastric cancer, had a CLDN18.2 expression level of 40%, 2+." (PMID 38604764, 2024).
gastric cancer (continued). "Randomized phase 2 (FAST, NCT01630083) and phase 3 trials (SPOTLIGHT, NCT03504397, and GLOW, NCT03653507) have demonstrated the clinical efficacy of zolbetuximab in combination with chemotherapy in patients with HER2-negative unresectable/recurrent gastric cancer showing high expression of CLDN18.2." (PMID 38724721, 2024). "CLDN18 has been identified as a target for therapy and intensive research in gastric cancer." (PMID 39409942, 2024). "Furthermore, the successful phase III clinical trial of zolbetuximab has proven the efficacy and safety of CLDN18.2 as a potential therapeutic target for gastric cancer." (PMID 39227365, 2024). "Gene Ontology (GO) enrichment analysis showed significant enrichment in extracellular matrix organization (GO0030198), extracellular structure organization (GO0043062), and collagen fibril organization (GO0030199) biological processes in CLDN18.2 gastric cancer cells co-cultured with CAFs." (PMID 38200591, 2024). "The present study demonstrated that CLDN18 positivity in PD-positive gastric cancers was 54.8% at 40% cut-off and 28.6% at 75% cut-off in primary tumors, and the frequency was slightly lower in disseminated lesions, showing positivity in 44% at 40% cut-off and 20.2% at 75% cut-off." (PMID 38724721, 2024). "The CLDN18-ARHGAP fusion gene is an oncogenic driver newly discovered in gastric cancer." (PMID 39164472, 2024). "CLDN18 expression was positively correlated with the metastatic parthenogenesis of the diffuse gastric cancer subtype and an independent prognostic factor for gastric cancer patients." (PMID 39682235, 2024). "Interestingly, a combination of CLDN18.2-negative status with high levels of CD4 + T cells or CD8 + T cells is predictive of better prognosis in gastric cancer." (PMID 37582713, 2023). "CLDN18 is overexpressed in some malignant cancers, like colon cancer and gastric cancer." (PMID 36969056, 2023). "This overexpression proved to be of critical clinical significance, where zolbetuximab, an IgG1 monoclonal antibody, could bind to claudin-18.2 and induce gastric cancer cell death via antibody-dependent and complement-dependent cytotoxicity." (PMID 37627123, 2023). "However, CLDN18 expression starts to decline in early gastric cancer or even in some intestinal chemosis of gastric tissue." (PMID 37582713, 2023). "The loss of claudin-18 not only results in TJ dysfunction and lack of proton barrier properties but also leads to numerous pathologies including gastritis, chronic inflammation, and gastric cancer, therefore claudin-18 has been identified as a targeted therapy candidate." (PMID 35893449, 2022). "In addition, patients with advanced gastric cancer also benefited from CLDN18.2-targeted CAR-T cells (CT041) in a phase 1 trial." (PMID 36620607, 2022). "Past research indicated that CLDN18.2 was a good marker of poor survival in gastric cancer and that the downregulation of CLDN18 may represent an early event of gastric carcinogenesis with an intestinal phenotype." (PMID 36620607, 2022). "Thus, it has the potential to be used in targeted therapy for gastric cancer patients with the CLDN18-ARHGAP26 fusion gene." (PMID 34716859, 2022). "In gastric cancer, CLDN18 can be employed as a tumor marker." (PMID 35281827, 2022). "CLDN18.2 is the dominant isoform of CLDN18 in normal gastric and gastric cancer tissues." (PMID 34834447, 2021). "Summaries of the positive rates of Claudin 18 in gastric cancer." (PMID 32668412, 2020). "In addition, diffuse gastric cancer had a greater proportion of CLDN18-ARHGAP fusions than intestinal gastric cancer (13.3%, 151/1,138 vs. 1.8%, 8/442; p < 0.001)." (PMID 32983960, 2020). "Moreover, gastric cancer patients with the CLDN18-ARHGAP fusion gene are more likely to be female or have a younger age, lymph node metastasis and advanced TNM stages." (PMID 32983960, 2020). "However, the clinical and prognostic meaning of the CLDN18-ARHGAP fusion in gastric cancer patients is unclear." (PMID 32983960, 2020).
gastric cancer (continued). "CLRN3 has been identified as a HNF4A transcriptional target in iPSC-derived hepatocytes, and CLDN18 has been confirmed as a GATA6 target in gastric cancer; therefore, we used these likely targets to test the regulatory potential of HNF4A and GATA6 in OE19 cells." (PMID 30962179, 2019). "The influence of claudin-3, claudin-7, and claudin-18 in gastric cancer patients were also studied." (PMID 31861759, 2019). "We firstly established the clinical relevant of CLDN18-ARHGAP26/6 in gastric cancer." (PMID 29961079, 2018). "Firstly, CDH17 and CLDN18 demonstrated homogeneous immunostaining in gastric cancer tissue." (PMID 27580354, 2016). "Combination of CDH17 and CLDN18 markers detected 92.5% of gastric cancer cases (98 of 106 cases)." (PMID 27580354, 2016). "According to hierarchical clustering applied to the threshold of CDH17 and CLDN18 IHC scores of primary lesions, gastric cancers could be classified into three subgroups." (PMID 27580354, 2016). "Furthermore, CLDN18 was also found to be focused in CLDN18–ARHGAP26 fusions in gastric cancer, which mediated epithelial disintegration." (PMID 27580354, 2016). "CDH17 and CLDN18 showed high specificity for gastric cancer cells." (PMID 27580354, 2016). "Intestinal-type CDH17 and gastric-type CLDN18 could be a useful combination to enable coverage of most gastric cancers that show a partial redundancy but primarily specific behavior." (PMID 27580354, 2016). "Claudin-18 expression is suppressed by miR-1303 in gastric cancer cells." (PMID 26061016, 2015). "Furthermore, gastric cancer patients showing downregulation of claudin 18 had a significantly worse survival, compared with patients with robust expression of this protein." (PMID 19142187, 2009). "Because of its highly restricted pattern, claudin-18 may therefore represent a useful target for therapy of gastric cancer, especially in those tumors that maintain high levels of this gene." (PMID 16836752, 2006). "However, it remains unclear whether and how autophagy influences CLDN18.2-targeted ADC therapy in gastric cancer, highlighting the need for further investigation." (PMID 39227365, 2024). "Additionally, Kyoto Encyclopedia of Genes and Genomes (KEGG) enrichment analysis revealed significant enrichment in the ECM-receptor interaction, focal adhesion, PI3K-Akt signaling pathway, and other signaling pathways in CLDN18.2 gastric cancer cells co-cultured with CAFs." (PMID 38200591, 2024). "Moreover, expression of CLDN18 was reduced in gastric cancer." (PMID 38201579, 2023). "Moreover, the CLDN18-ARHGAP26 fusion protein may became a novel target for the treatment of gastric cancer patients in the future." (PMID 34716859, 2022). "Thus, based on our preclinical findings, ZL-1211 may show better clinical efficacy in patients with CLDN18.2-expressing gastric cancer than clinical leading benchmark." (PMID 36922936, 2022). "The low expression of CLDN18 in gastric cancer could be used as a marker of adverse outcome." (PMID 34721537, 2021). "However, 51.5% of gastric cancer tissues exhibited reduced expression of claudin-18." (PMID 31861759, 2019). "However, a limitation of this study was that only MKN74 could be examined, because it was the only differentiated gastric cancer cell line which expressed claudin-18 as far as we examined." (PMID 24073219, 2013). "However, claudin-18 is downregulated in intestinal-type gastric cancer." (PMID 23822740, 2013). "Zolbetuximab, an anti-CLDN18.2 antibody, has shown improved survival in a Phase III trial for advanced gastric cancer, validating this approach." (PMID 40687428, 2025). "In gastric cancer, agents such as the anti-HER2 antibody trastuzumab, the anti-angiogenic drugs ramucirumab and apatinib, and the CLDN18.2-directed monoclonal antibody zolbetuximab have ushered in an era of personalized treatment." (PMID 40977700, 2025).
gastric cancer (continued). "In esophageal and gastric cancers, targets such as HER2 (NCT02713984), EGFR, CEA (NCT02349724), MSLN (NCT03747965), CLDN18.2 (NCT05472857), and NKG2D have shown effective antitumor effects in preclinical and early clinical trials." (PMID 40909948, 2025). "The present study demonstrated that CLDN18 positivity in G/EGJ with PM was 31.1% at 75% cut-off in primary tumors, in agreement with a recent study on gastric cancer with PM which reported a positivity rate of 28.6%." (PMID 40205072, 2025). "The therapeutic landscape of gastric cancer has undergone a paradigm shift with the introduction of antibody-based therapies targeting biomarkers such as HER2, PD-L1, and CLDN18.2." (PMID 41614808, 2025). "We constructed gastric cancer cell lines AGS and NUGC4 stably expressing GFP or CLDN18.2-GFP, then injected these cells into mice through the tail vein, and determined the adhesion of gastric cancer cells in the lung tissue using IHC." (PMID 38200591, 2024). "Our results showed that CAFs promoted the adhesion of CLDN18.2-GFP gastric cancer cells to lung endothelial cells, and that tumor cells formed more and larger cell clusters compared with the stable GFP gastric cancer cell group." (PMID 38200591, 2024). "In gastric cancer, the fusion of ARHGAP26 and the claudin-18 gene (CLDN18) led to the translation of an abnormal fusion protein, which promoted the development of gastric cancer." (PMID 37175461, 2023). "In our investigation of the immunological microenvironment in gastric cancer (GC) patients, we observed strong correlations between CLDN18.2 expression levels and CD4 + T cells, CD8 + T cells, and B cells according to the TISIDB database analysis (all p < 0.05)." (PMID 37582713, 2023). "In vitro experiments have shown that the presence of the CLDN18-ARHGAP26 fusion gene increases the migration and invasion ability of gastric cancer cells, as well as the resistance of tumor cells to chemotherapy drugs." (PMID 34716859, 2022). "It is noteworthy that the high affinity of the CLDN18-ARHGAP26 fusion protein for the cell membrane, as well as its exclusive expression in gastric cancer cells provide new opportunities for targeted therapies." (PMID 34716859, 2022). "Abnormal expression of CLDN18 has been reported in gastric cancer (GC)." (PMID 32668412, 2020). "In the GSE55696 dataset, CLDN18 expression was decreased in low grade intraepithelial neoplasia (LGIN), high grade intraepithelial neoplasia (HGIN), and early gastric cancer (EGC) tissues compared to chronic gastritis tissues." (PMID 32668412, 2020). "As in mouse gastric cancer cells, human gastric cancer cells (NUGC4, SNU-719, and SNU-638) stably expressing CLDN18-ARHGAP26 demonstrated a higher degree of migration ability than those expressing an empty vector (P < 0.001, Wilcoxon signed rank test)." (PMID 30361512, 2018). "To gain functional insights into the poor prognostic role of CLDN18-ARHGAP26 in gastric cancer, we stably expressed CLDN18-ARHGAP26 in mouse gastric cancer cells." (PMID 30361512, 2018). "In the present study, 26 of the 254 gastric cancers examined in our cohort had CLDN18-ARHGAP26/6 fusions, and 22 of the 26 gastric cancers with the fusions were DGCs (22 cancers of 172 DGCs, 12.8%)." (PMID 30034621, 2018). "A recent study shows that a fusion gene between fragments of claudin 18 and GRAF1, CLDN18-ARHGAP26, found in gastric cancer, impairs epithelial integrity and induces EMT." (PMID 27588930, 2017). "Hierarchical clustering classified gastric cancers into three subgroups, CDH17(++)/CLDN18(+/−), CDH17(++)/CLDN18(++) or CDH17(+)/CLDN18(+), and CDH17(−)/CLDN18(++/+/−)." (PMID 27580354, 2016). "Combination of CDH17 and CLDN18 covered 50 cases out of 56 (89.3%), which indicated that the coupling of markers for CDH17 and CLDN18 provides an opportunity to detect gastric cancer using specific antibodies." (PMID 27580354, 2016).